PMS2P1 (PMS1 homolog 2, mismatch repair system component pseudogene 1)
Synonyms: PMS2L13; PMS3; PMS8; PMSR2; PMSR1; formerly PMS2L6; PMS2L8; PMS2L7; PMS2L1
Gene: Transcribed unprocessed pseudogene on chromosome 7 (100,328,836 to 100,335,860, reverse strand). Ensembl gene ENSG00000078319.
Diseases named in the same sentence as PMS2P1 in open-access papers:
PMS2P1 is named in the same sentence as 3 diseases in open-access papers, as found by Europe PMC text mining. Sharing a sentence is not in itself a finding about the gene and the disease. The quoted sentences say what the papers report.
childhood cancer (1 paper, 2020). "Only one study described the association of a nonsense homozygous mutation in the PMS2P1 gene (c.2428C>T, Arg802X) with a supratentorial primitive neuroectodermal tumour in three siblings, suggesting the involvement of PMS2P1 mutations in childhood cancer." (PMID 32756484, 2020).
cancer (1 paper, 2020). A tumor composed of atypical neoplastic, often pleomorphic cells that invade other tissues. "The authors concluded that although PMS2P1 mutations in the CRC may be rare, their involvement in childhood cancers is underestimated." (PMID 32756484, 2020).
PMS2P1 also shares sentences with these, for which no sentence is quoted: primitive neuroectodermal tumour (1 paper).